KLF4 (KLF transcription factor 4)
Diseases named in the same sentence as KLF4 in open-access papers (continued):
Sharing a sentence is not in itself a finding about the gene and the disease.
breast cancer (continued). "In breast cancer cells, KLF4 recruits HDAC2 and HDAC3 to the VEGF promoter, inhibiting its angiogenic potential." (PMID 36761967, 2023). "After confirming that KLF4 mediates VM in aggressive breast cancer cells, we investigated the regulatory mechanism of human KLF4 expression." (PMID 37762678, 2023). "In another study, researchers synthesized a novel compound that has the potency to inhibit PRMT5, disrupt the interaction of PRMT5 and KLF4, and suppress breast cancer development." (PMID 38136401, 2023). "KLF4 inhibited the breast cancer cells growth, metastasis, and invasion through inhibition of Snail, estrogen receptor, and epidermal growth factor receptor." (PMID 37031197, 2023). "Recently, the methylation of stemness factor KLF-4 (Kruppel-like factor-4) by PRTM5 was shown in breast cancer." (PMID 38136401, 2023). "Kenpaullone, a potent inhibitor of CDK1/cyclin B and GSK-3β, inhibited the proliferation and migration of breast cancer cells and induced cell death by downregulating KLF4." (PMID 37031197, 2023). "In breast cancer, inhibition of transcription factor KLF4 (Kruppel-like factor 4) can suppress the self-renewal of breast CSCs, suggesting that KLF4 plays a part in maintaining the characteristics of CSCs with the involvement of Notch signaling pathway." (PMID 36153608, 2022). "It was reported that miR-7 expression can decrease KLF4 expression and suppress breast cancer cell metastasis." (PMID 36012357, 2022). "Genes related with MAP kinase pathways which include, GRMI, KLF4 etc have clear link with drug resistance in breast cancer." (PMID 36415633, 2022). "KLF4 participates in the occurrence and progression of breast cancer, lung cancer, prostate cancer, colorectal cancer and other cancers." (PMID 35027543, 2022). "It has shown that KLF4 can regulate cell proliferation, migration, and invasion in multiple cancers, including breast cancer, gastrointestinal cancer, and esophageal cancer." (PMID 35154316, 2022). "Studies confirmed that there are differences in KLF4 expression in human tumor tissues, including prostate cancer, liver cancer, and breast cancer." (PMID 35027543, 2022). "KLF4 is highly expressed in >70% breast cancer patients, human breast cancer cell lines, and mouse mammary cell-derived stem cells." (PMID 35740529, 2022). "In breast cancer, the mRNA expression levels of KLF4/5/7/8/9/10//12/15 were significantly down-regulated in multiple datasets." (PMID 35033064, 2022). "Studies have shown that KLF4 acts as a tumor suppressor in colorectal cancer, gastric cancer, and bladder cancer while playing an oncogenic role in breast cancer and skin cancer." (PMID 35383144, 2022). "Other studies initiated in mice revealing host genes that impact metastatic competence in breast cancer include Klf4, Arntl2, and Zbtb16 also have clinical associations." (PMID 35727842, 2022). "Next, we investigated the expression of KLF4, which is important for the maintenance of breast cancer stem cell features and the promotion of the cell migration and invasion." (PMID 35085258, 2022). "KLF4 is also required for the maintenance of breast cancer stem cells and for cell migration and invasion." (PMID 36078038, 2022). "miR-7 also targets Krüppel-like factor 4 (KLF4) in breast cancer stem-like cells (CSC) and impedes their metastasis to the brain." (PMID 36555120, 2022). "On the other hand, KLF4 also inhibits the invasion and metastasis of breast cancer by inhibiting the EMT process." (PMID 34040532, 2021). "The KLF4 expression was evaluated in different breast cancer cells, including the MDA-MB-468, MDA-MB-231, MCF-7 and T47D breast cancer cells by immunofluorescent staining and Western blotting." (PMID 34150611, 2021). "To determine the level of KLF4 in breast cancer tissues, we determined the KLF4 expression in 50 breast cancer and adjacent normal tissues by immunohistochemical (IHC) staining." (PMID 34150611, 2021).
breast cancer (continued). "Both KLF4 and miR-206 act as pro-survival factors and promote anoikis resistance and tumorigenesis in breast cancer." (PMID 33435156, 2021). "Some studies reported that KLF4 is upregulated in breast cancer tissues, while others found that KLF4 is downregulated." (PMID 34150611, 2021). "In 414 breast cancer cases, both KLF4 and SLC7A11 mRNA levels were negatively related to patients’ post progression survival (PPS); that is, the higher the KLF4 or SLC7A11 mRNA expression level, the lower the survival rate after progression." (PMID 34040532, 2021). "In breast cancer, KLF4 is enriched in breast cancer stem cells and transcriptionally increases miR-206 that targets PDCD4." (PMID 33435156, 2021). "The results suggested that the level of KLF4 was related to the PTX sensitivity in breast cancer cells." (PMID 34150611, 2021). "DIM can effectively decrease the expression of DNMT1 and the methylation level of KLF4 in breast cancer cells, and then promote the expression of KLF4." (PMID 34150611, 2021). "In breast cancer, KLF4 knockdown reduced ALDH1+ CSCs and mammosphere formation in vitro in MCF7 and MDA-MB-231 cells." (PMID 34680284, 2021). "Using PROGgeneV2 webtool, we found the high expression of cMYC, KLF4, and PTGES2 are associated with poor survival whereas the high expression of PTGDS is associated with better survival in patients with breast cancer." (PMID 33494773, 2021). "In summary, our findings demonstrate that the expression of DNMT1 and the methylation level of KLF4 promoter increased, while the expression of KLF4 decreased in breast cancer tissues." (PMID 34150611, 2021). "Collectively, our data indicated that DNMT1-mediated hypermethylation of KLF4 promoter leads to downregulation of KLF4 in breast cancer." (PMID 34150611, 2021). "The ferroptosis inducer SAS or the knockdown of KLF4 by siRNA enhances the proliferation inhibitory effect of Polyphyllin III on breast cancer by downregulating xCT and promoting ferroptosis." (PMID 34040532, 2021). "In breast cancer, where KLF4 has been characterized as an oncogene, KLF4 directly induced transcription of phosphofructokinase, enhanced glucose intake, and increased lactate production." (PMID 33917010, 2021). "Consistently, high expression of ATXN3 and KLF4 serve as indicators of an adverse prognosis in breast cancer." (PMID 34575114, 2021). "Aberrant overexpression of KLF4 is found in many breast cancer cells, indicating its relationship with early formation and steam cell property maintenance in breast cancer." (PMID 34040532, 2021). "We found that Mir145 was significantly downregulated in ATF3-induced mammary tumors, and that its direct targets Klf4 and Sox2 were significantly upregulated." (PMID 33652981, 2021). "Our data showed that the expression of DNMT1 was increased, and the methylation level of CpG sites (−148 bp) in the KLF4 promoter was increased while the KLF4 expression was significantly decreased in breast cancer tissues." (PMID 34150611, 2021). "In our study, we found that the expression of KLF4 was significantly decreased in breast cancer tissues." (PMID 34150611, 2021). "To further investigate the mechanism of action of DIM in enhancing PTX sensitivity, we determined the expression levels of DNMT1 and KLF4 in breast cancer MCF-7 and T47D cells after treatment with DIM." (PMID 34150611, 2021). "Then, KLF4 and xCT protein levels were measured in different breast cancer cell lines using western blotting analysis." (PMID 34040532, 2021). "Some previous studies showed that the expression of KLF4 was reduced, while others reported that KLF4 expression was increased in breast cancer tissues." (PMID 34150611, 2021). "Our preliminary work demonstrated that the expression of KLF4 is related to PTX sensitivity of breast cancer MCF-7 cells." (PMID 34150611, 2021).
breast cancer (continued). "Further, the overexpression of KLF4 in MDA-MB-231 breast cancer cells restored E-cadherin levels, induced an epithelial morphology, and suppressed migration and invasion, similar to previous observations in these cells for another MET-TF, GRHL2." (PMID 34680284, 2021). "Expected staining patterns were demonstrated in control human tissues: seminoma for OCT4, normal skin for SOX2, seminoma for NANOG, breast cancer for KLF4 and normal prostatic tissue for c-MYC." (PMID 34685477, 2021). "Positive staining was demonstrated on sections of control human tissues: tonsil for CD44, seminoma for OCT4 and NANOG, skin epidermis for SOX2, breast carcinoma for KLF4, and colon mucosa for c-MYC." (PMID 34685477, 2021). "Positive controls showed expected staining for OCT4 and NANOG in seminoma, SOX2 in skin, KLF4 in breast carcinoma, and c-MYC in normal colon." (PMID 33816543, 2021). "The methylation level of KLF4 promoter was measured in breast carcinoma tissues (n = 5) and adjacent normal tissues (n = 5) by the MassArray methylation assay." (PMID 34150611, 2021). "Aligning with its role as a pluripotency transcription factor, KLF4 can stimulate stem cell properties in breast cancer cells." (PMID 32552913, 2020). "To validate the therapeutic relevance of KLF4 in breast cancer DNA repair/DNA damage targeting treatment, we have conducted an in vivo mouse xenograft study by using murine 4T1 model, which harbors wild‐type BRCA1 expression." (PMID 33231937, 2020). "They found that KLF4-dependent inhibition of migration and invasion of breast cancer cells is regulated by miR-1233-3p which is a target of circEHMT1." (PMID 33266506, 2020). "Results from further clonogenic assay showed that depletion of KLF4 in breast cancer cells significantly enhanced that efficacy of olaparib and other chemotherapy agents such as doxorubicin and cisplatin in killing cancer cells." (PMID 33231937, 2020). "Since CDR1as has been previously shown to modulate EGFR and KLF4 in breast cancer development, and these genes play importat roles also in the skin, it will be interesting to assess its potential tumor suppressive effect in the context of cSCC." (PMID 32108138, 2020). "Nuclear factor I-C (NFI-C) appears to be an essential factor for the maintenance of epithelial differentiation and inhibits EMT and metastasis of breast cancer cells by regulating KLF4." (PMID 33266506, 2020). "The study of the role of KLF4 in glycolytic metabolism and proliferation in breast cancer cells revealed that KLF4 is a stimulator of glycolytic metabolism." (PMID 33266506, 2020). "Cy3G inhibited the EMT process in these cells and significantly suppressed the migration and invasion of breast cancer cells (P ≤ 0.05) by upregulating Krüppel-like factor 4 (KLF4) expression at protein level." (PMID 33240028, 2020). "It degrades Krueppel-like factor 4 (KLF4) to suppress the breast cancer progression via p38 mitogen-activated protein kinase pathway." (PMID 32226545, 2020). "Recent studies have indicated that KLF4 was required for the maintenance of cancer stem cells in osteosarcoma, breast cancer, and prostate cancer." (PMID 33052880, 2020). "AGPAT9 inhibits breast cancer cell proliferation, migration and invasion both in vitro and in vivo through the KLF4/Homo sapiens longevity assurance homolog 2 of yeast LAG1 (LASS2)/ vacuolar-H+-ATPase (V-ATPase) signaling pathway." (PMID 33266506, 2020). "Other mechanisms suggesting protective role of KLF4 in breast cancer involve human 1-acylglycerol-3-phosphate O-acyltransferase 9 (AGPAT9)." (PMID 33266506, 2020). "The expression of KLF4, required for breast cancer stem cell (CSC) maintenance, was also significantly repressed upon combination treatment." (PMID 32720467, 2020). "Cisplatin treatment elevates KLF4 protein levels, which led to reduced sensitivity of breast cancer cells to this drug." (PMID 33266506, 2020).
breast cancer (continued). "For example, the lncRNA PVT1 regulates malignant behavior in xenograft models of breast cancer cells, whereas small nucleolar RNA host gene 5 knockdown restrains the malignant phenotype of gastric cancer cells by targeting the miR-32/KLF4 axis." (PMID 31789416, 2020). "It should be noted that KLF4 is a favorable prognostic indicator for patients with other subtypes of breast cancer as well (classified on the basis of the estrogen receptor (ER) and HER2 status)." (PMID 33266506, 2020). "Although the role of KLF4 in breast cancer remains controversial, KLF4 has been reported to be an EMT suppressor in breast cancer cells." (PMID 33240028, 2020). "The role of KLF4 in breast cancer is complex; it has been reported that KLF4 has dual function as either a tumor suppressor or an oncogene, in a context-specific manner." (PMID 33266506, 2020). "Together, our findings suggest that LINC00115 promotes breast cancer metastasis through modulating the expression of miR‐7 and KLF4." (PMID 32175684, 2020). "For instance, Krüppel-like factor 4 (KLF4) maintains the expression of E-cadherin in breast cancer cells, and reduces the expression of Slug in prostate cancer to suppress metastasis." (PMID 32824207, 2020). "There are many molecular pathways and cellular processes responsible for the involvement of KLF4 in breast cancer." (PMID 33266506, 2020). "Other studies revealed interesting mechanisms of KLF4 regulation in breast cancer cells, involving DEAD-BOX (DDX) RNA helicase (DDX3X)." (PMID 33266506, 2020). "LINC00115 also reduces the expression of KLF4, which is a direct target of miR‐7 and is involved in breast cancer metastasis." (PMID 32175684, 2020). "Cy3G is a potential anticancer reagent as it can inhibit EMT and breast cancer cell migration and invasion by upregulating KLF4." (PMID 33240028, 2020). "For example, miR‐7 inhibits the ability of breast cancer stem‐like cells to spread into the brain through modulating KLF4; miR‐7 directly inhibits SETDB1 and reverses the epithelial–mesenchymal transition of breast cancer stem‐like cells." (PMID 32175684, 2020). "This miRNA has been identified as a tumor suppressor in breast cancer, and one of its direct targets, KLF4, is an oncogene in breast cancer." (PMID 32175684, 2020). "Accumulating evidence suggests that noncoding microRNA (miR-7) is a breast cancer suppressor because it inhibits Kruppel-like factor-4 (KLF-4), which is one of the oncogenes that enhance breast cancer growth." (PMID 32143670, 2020). "This study demonstrates that cyanidin-3-O-glucoside, one of the most widely distributed anthocyanin family members in edible fruits, can inhibit EMT, and cell migration and invasion of breast cancer cells by indirectly regulating KLF4 expression." (PMID 33240028, 2020). "Expected staining patterns were demonstrated in the human positive control tissues: seminoma for OCT4 and NANOG, normal skin for SOX2, breast carcinoma for KLF4, and normal colon for c-MYC." (PMID 32019273, 2020). "Positive controls demonstrated the expected staining pattern for OCT4 and NANOG in seminoma, SOX2 in normal skin, KLF4 in breast carcinoma, and c-MYC in normal colon." (PMID 32019273, 2020). "Human tissues used for positive controls demonstrated positive staining of OCT4 and NANOG on sections of seminoma, SOX2 on skin, KLF4 on breast carcinoma, and c-MYC on colon." (PMID 32850316, 2020). "Human tissues for positive controls showed the expected staining patterns: for OCT4 and NANOG on seminoma, SOX2 on skin, KLF4 on breast carcinoma, and c-MYC on colon." (PMID 32850316, 2020). "KLF4 also functions as an oncogene to promote proliferation of breast cancer and bladder cancer cells in the presence of RASV12-Cyclin-D1 signaling or the absence of p21CIP1." (PMID 30933982, 2019).
breast cancer (continued). "Previous studies have indicated that the E3 ligase VHL and FOXB33 promoted KLF4 degradation in breast cancer." (PMID 30658712, 2019). "This inhibition was shown to be negatively regulated by KLF4 (Kruppel-like factor 4) transcription factor and its target gene, p21, in transgenic mouse model of breast cancer." (PMID 31416295, 2019). "Knockdown of KLF4 gene suppressed breast cancer cell migration, invasion, and colony formation in vitro and inhibited tumorigenesis in immunocompromised mice." (PMID 31245293, 2019). "According to a study of breast cancer cell lines, miR-7 expression is involved in the migration and invasion of tumor cells, through regulation of the expression of the KLF4 gene." (PMID 31603918, 2019). "MiR-7-5p can also inhibit cell metastasis by targeting focal adhesion kinase (FAK) and Kruppel-like factor 4 (KLF4) in breast cancer." (PMID 31832068, 2019). "Multiple researches showed that KLF4 was downregulated in colon cancer, lung cancer, esophageal cancer, bladder cancer, but upregulated in breast cancer." (PMID 31969824, 2019). "Since KLF4 acts as an oncogene in most breast cancer cells, we decided to check the effect of the combinatorial regimen in downregulating the oncogene at the transcriptional level." (PMID 29899271, 2018). "In breast cancer patients, decrease of SIRT1 was associated with reduced PRRX1 but increased KLF4, and the latter was positively correlated with distal metastases (P<0.001, χ2 test)." (PMID 30038266, 2018). "We show that DDX3X‐mediated repression of KLF4 promotes expression of S‐phase inducing genes in MCF7 breast cancer cells." (PMID 29782654, 2018). "We next did immunohistochemical analysis of KLF4 on 122 subjects of breast cancer to validate the association between KLF4 and SIRT1 and to elucidate the clinical relevance of KLF4 overexpression in patients with distal metastases." (PMID 30038266, 2018). "Other factors involved in regulating stem cell renewal and metastasis were also upregulated in KLF4 overexpressing breast cancer cells including c-MYC, SOX9, BMI1, Z1B1, SLUG, TWIST and N-CADHERIN." (PMID 30613353, 2018). "The apoptosis rate of SK-BR-3 breast cancer cells is increased and cell tumorigenicity is decreased by upregulation of KLF4." (PMID 29848383, 2018). "In this context, the induction of mesenchymal phenotype in vitro and metastasis in vivo in breast cancer cells requires downregulation of KLF4." (PMID 29747682, 2018). "In this study, ZNF32 showed the ability to facilitate mammosphere formation and the expression of ALDH1, OCT4, Nanog and KLF4 in breast cancer cells." (PMID 30478301, 2018). "Knockdown of DDX3X in MCF7 breast cancer cells induces expression of KLF4, alters KLF4 mRNA exon usage and down‐regulates cell cycle factors genes, CCNA2 and CDK2, leading to reduced cell growth." (PMID 29782654, 2018). "In breast cancer, the function of KLF4 is controversial, with reports showing both oncogenic and tumor-suppressive roles." (PMID 29789534, 2018). "Depletion of SIRT1 remarkably increases the number of ALDH1+ CSCs, elicits partial MET, and promotes lung metastasis by upregulating KLF4 in human and mouse breast cancer cells." (PMID 30038266, 2018). "More recently, it was shown that KLF4α is able to antagonize the function of KLF4 in breast cancer and that an increased ratio of KLF4α/KLF4 induced cancer cell proliferation." (PMID 30555344, 2018). "In breast cancer and osteosarcoma, upregulation of KLF4 enhanced chemoresistance and inhibited cell apoptosis." (PMID 30176890, 2018). "Recent studies have shown that the anticancer properties of benzyl isothiocyanate, a chemopreventive constituent derived from cruciferous vegetables, were enhanced by KLF4 knockdown in breast cancer cells." (PMID 29899271, 2018).